VDR (vitamin D receptor)
Diseases named in the same sentence as VDR in open-access papers (continued):
Sharing a sentence is not in itself a finding about the gene and the disease.
gestational diabetes mellitus (28 papers, 2015 to 2025). "Another Chinese study suggested a possible correlation between maternal and fetal VDR SNPs and the risk of gestational diabetes mellitus." (PMID 40944150, 2025). "A recent meta-analysis showed an increased susceptibility to gestational diabetes mellitus (GDM) associated with VDR ApaI (rs7975232) and FokI (rs2228570) polymorphisms." (PMID 35627905, 2022). "In our study the PICO was shown as follow: P: Gestational diabetes mellitus; I: vitamin D receptor (VDR) polymorphisms; C: control people; O: susceptibility." (PMID 34903261, 2021). "A systematic review and a meta-analysis were done to compare the distribution of Vitamin D receptor gene polymorphisms in gestational diabetes mellitus patients with those in controls using allelic, codominant, dominant, and recessive models." (PMID 33383970, 2020). "High heterogeneity existed in studies on the association of vitamin D receptor genes rs1544410, rs2228570, and rs731236 with gestational diabetes mellitus, and the most common sources of heterogeneity were the year of publication and matching." (PMID 33383970, 2020). "The aim of this study was to summarize available evidence on the association between polymorphisms of Vitamin D receptor genes and susceptibility to gestational diabetes mellitus." (PMID 33383970, 2020). "The rs1544410 SNP of the VDR gene has been associated with increased insulin secretion in women with post-gestational diabetes mellitus, suggesting a preventive role in developing post-gestational diabetes mellitus." (PMID 39408801, 2024). "It has been suggested that VDR polymorphism could be associated with the occurrence of gestational diabetes, preterm labor, recurrent miscarriages, gestational cholestasis, and intrauterine fetal restriction that often coexisted with PE and placental insufficiency." (PMID 34574039, 2021). "However, the relationship between VDR gene polymorphism and gestational diabetes susceptibility may provide new ideas for the prevention of gestational diabetes in the future." (PMID 33383970, 2020). "This study aimed to examine the expression of the vitamin D receptor in the placenta of patients with gestational diabetes mellitus and healthy women." (PMID 41007445, 2025). "The correlation between VDR gene rs739837 polymorphism and susceptibility to T2DM and gestational diabetes mellitus (GDM) pointed out that the VDR gene rs739837 polymorphism is significantly correlated with susceptibility to T2DM." (PMID 38650715, 2024). "In human studies, VDR overexpression and VD treatment have been shown to reduce apoptosis and mitochondrial damage in patients with gestational diabetes." (PMID 34768761, 2021). "The observed increase in the placental expression of the vitamin D receptor in gestational diabetes mellitus may be an adaptive response to metabolic stress, unrelated to maternal vitamin D levels." (PMID 41007445, 2025). "This study demonstrates that placental VDR expression is significantly increased in pregnancies complicated by gestational diabetes mellitus, independent of maternal serum vitamin D levels." (PMID 41007445, 2025). "The association between the vitamin D receptor (VDR) gene and gestational diabetes mellitus (GDM) has not been investigated in Turkish pregnant women." (PMID 31096931, 2019).
rheumatoid arthritis (28 papers, 2017 to 2025). A chronic, systemic autoimmune disorder characterized by inflammation in the synovial membranes and articular surfaces. "Numerous studies across different populations have explored the relationship between VDR polymorphisms and rheumatoid arthritis (RA)." (PMID 40278307, 2025). "Through literature review, we found that VDR-Fok I polymorphism is associated with susceptibility to rheumatoid arthritis in the European population." (PMID 40370697, 2025). "In this context, higher vitamin D concentration was shown to be associated with higher VDR promoter methylation in rheumatoid arthritis (RA) patients." (PMID 36980815, 2023). "The purpose of current study was to evaluate the effect of vitamin D level and VDR gene polymorphism on rheumatoid arthritis and osteoarthritis." (PMID 31011579, 2019). "Nevertheless, some VDR polymorphisms have been linked to some musculoskeletal diseases, such as idiopathic scoliosis susceptibility or curve severity, herniation and spinal tissues degeneration and rheumatoid arthritis." (PMID 34456969, 2021). "This study aimed to compare vitamin D receptor (VDR) FokI and TaqI genotypes in terms of parathyroid hormone (PTH) and some biomarkers of inflammation and susceptibility to rheumatoid arthritis (RA) disease." (PMID 37858254, 2023). "For other inflammatory joint disease–rheumatoid arthritis (RA)–the GG genotype of the VDR rs1544410 polymorphism was found to be associated with less severe disease in one study, and the second study highlighted higher activity for the GG and the AG rs1544410 genotypes." (PMID 36292758, 2022). "An in vitro study reported the hyperexpression of VDR in the areas of erosion of late-stage rheumatoid arthritis cells." (PMID 34884724, 2021). "Vitamin D receptor (VDR) polymorphisms also impact ESR levels, and in systemic sclerosis patients, BglI and ApaI polymorphisms were associated with an increased ESR, while the BsmI polymorphism was associated with an increased ESR in rheumatoid arthritis patients." (PMID 37238156, 2023).
skin cancer (28 papers, 2008 to 2026). "For instance, a knockout VDR mouse model showed an increased risk of developing skin cancer, which suggests VDR potentially functioning as a tumor suppressor." (PMID 34306760, 2021). "Taken together, these results indicate that dysfunctional VDR signalling pathways are implicated in skin cancer development and progression." (PMID 25887475, 2015). "In a mouse model, dysfunctional VDR increased susceptibility to skin cancer following exposure to 7,12-dimethylbenz[a]anthracene (DMBA) or UV light." (PMID 25887475, 2015). "Most of the studies examining associations between skin cancer and polymorphisms in the vitamin D metabolism analyzed polymorphisms in the VDR gene." (PMID 22576141, 2012). "In most studies that investigated the association of polymorphisms in the vitamin D system and skin cancer risk VDR gene SNPs were assessed." (PMID 22576141, 2012). "We have also reported significant associations between VDR polymorphisms and incidence of skin cancer." (PMID 22276021, 2009). "Further studies on the role of VDR polymorphisms in skin cancer development could be useful to better understand these associations." (PMID 22276021, 2009). "Since vitamin D exerts a function of engagement of its receptor VDR, it is likely that some SNPs of the VDR gene affect the ability of interacting with its ligand, which ultimately would lead to different levels of the biologic activity of vitamin D and increase skin cancer risk." (PMID 32753685, 2020). "VDR−/− mice exhibit reduced rates of thymine-dimer repair and apoptosis in UV-exposed skin and these dysfunctional epidermal repair pathways coincided with an enhanced susceptibility to the development of skin tumours induced by chronic UV irradiation or by a chemical carcinogen." (PMID 23049920, 2012). "This opens the door to preserving the benefits of VDR signaling while preventing solar radiation damage, bringing a new viewpoint for designing future strategies in skin cancer prevention and treatment." (PMID 41901339, 2026). "The first study suggesting a role for VDR-dependent lncRNAs in skin cancer protection was published in 2014 by Bikle and colleagues." (PMID 40724881, 2025). "Additional research is required to confirm the potential role of VDR gene in skin cancer incidence and to explore their interaction with sun exposure." (PMID 32753685, 2020). "Vitamin D, partly mediated through the vitamin D receptor (VDR), has potential therapeutic applications in skin cancer." (PMID 33255834, 2020). "Although at this point the role of vitamin D per se in the prevention of skin cancer remains uncertain, animal studies over the past decade have demonstrated a convincing role for the vitamin D receptor (VDR) in preventing skin cancer." (PMID 24202452, 2013). "For instance, since FokI is a vitamin D receptor gene and vitamin D is considered to be a protective factor in certain cancers, such as skin cancer, supplementation with vitamin D may be used as adjuvant therapy in cancer patients." (PMID 36874118, 2023). "Regarding the polymorphisms in the VDR gene, no significant main effects were observed between the BsmI or ApaI polymorphism genotypes and the skin cancer risk in the multinomial logistic regression model." (PMID 33255834, 2020). "Even though the role of sun exposure has been demonstrated, it should be note that VDR knockout (KO) mice develop UVB-induced skin cancers more rapidly and more frequently than wild-type mice, suggesting a potential protective role for 25OHD against non-melanoma skin cancers." (PMID 25376735, 2014). "Thus although the role of VDR in protecting us from skin cancer is established, we still have much to learn about the precise mechanisms by which it does so." (PMID 24202452, 2013).
skin cancer (continued). "A study that focused on the role of vitamin D receptor (VDR) polymorphisms in non-melanoma skin cancer development is also worth mentioning, since it reported a possible relationship between the two, highlighting the role of vitamin D in skin cancer." (PMID 37237973, 2023). "Ultraviolet (UV) radiation is involved in almost all skin cancer cases, but on the other hand, it stimulates the production of pre-vitamin D3, whose active metabolite, 1,25-dihydroxyvitamin D3 (1,25VD3), plays important physiological functions on binding with its receptor (vitamin D receptor, VDR)." (PMID 27058533, 2016). "However, recent findings that mice lacking the VDR are predisposed to skin cancer has brought to the fore the question of how the VDR is protective." (PMID 24202452, 2013). "Additional studies on mice have reported that VDR knockout mice exposed to oral 7, 12-dimethylbenzanthracene (DMBA) had increased sensitivity to develop chemically induced skin tumors." (PMID 34306760, 2021). "However, we also found new and interesting results in relation to VDR polymorphisms and skin cancer risk: No significant main effects were observed when the BsmI or ApaI polymorphisms were studied alone, but there were significant and interesting results when adjusted for stratum age and gender." (PMID 33255834, 2020). "Both VDR and GRHL1 have been studied in the context of skin cancers." (PMID 39063155, 2024). "To understand the role that VDR might be playing in its protective actions against chemical and UVB induced skin cancer we have examined three interacting mechanisms." (PMID 24202452, 2013). "The skin provides the best examples in that hair follicle cycling requires the VDR but not 1,25(OH)2D, and chemical‐ and UVB‐induced skin cancer occur in the Vdr null mouse but not in the Cyp27b1 null mouse." (PMID 34950833, 2021). "In the absence of 1,25(OH)2D, the VDR/RXR heterodimer activates genes regulating hair follicle cycling and skin tumor suppression." (PMID 34950833, 2021).
hyperparathyroidism (27 papers, 2005 to 2026). Hyperfunction of the parathyroid glands resulting in the overproduction of parathyroid hormone. "Considering the role of vitamin D receptor (VDR) polymorphisms in hyperparathyroidism, it is plausible that VDR polymorphisms also contribute to the development of brown tumors." (PMID 41036144, 2025). "The expression of CaSR, VDR and its relationship with the main laboratory parameters, the clinical variant of hyperparathyroidism, and the morphological substrate were studied." (PMID 37448244, 2023). "The molecular mechanisms by which Bsm I VDR polymorphisms influence hyperparathyroidism have been linked to presence of b alleles." (PMID 29415666, 2018). "In addition, association between VDR and CaSR were also confirmed in patients with hyperparathyroidism (p = 0.000)." (PMID 42314434, 2026). "In uremia, severe hyperparathyroidism is characterized by low parathyroid expression of CaR and VDR." (PMID 23094155, 2012). "All mice were fed a rescue diet enriched with calcium, phosphorus, and lactose to prevent hyperparathyroidism in VDR mutants, and were killed at 4 weeks of age after double fluorochrome labeling." (PMID 22319626, 2012). "A common molecular genetic mechanism for the development of hyperparathyroidism with a predominance of a morphological substrate in the form of adenoma or hyperplasia has been found to reduce the frequency of maintaining normal VDR expression in PTG (up to 7–13%), p<0.01." (PMID 37448244, 2023). "Calcitriol and its analogs such as paricalcitol (19-nor-1α,25(OH)2D2) that activate vitamin D receptor (VDR) are commonly used to manage hyperparathyroidism secondary to CKD." (PMID 20169119, 2010).
liver disease (27 papers, 2012 to 2026). "Single nucleotide polymorphisms (SNPs) in the VDR gene have been associated with liver diseases, including AIH, PBC, HBV infection, and HCC, and with the rapid progression of fibrosis in patients with HCV infection, PBC, and NAFLD." (PMID 37511164, 2023). "Our recent study demonstrated an association between polymorphisms of the VDR gene and cytokine levels, the severity of liver disease, and survival in patients with liver cirrhosis." (PMID 35955597, 2022). "Multiple studies have demonstrated that VDR polymorphisms are associated with the occurrence of a wide range of liver disorders." (PMID 32296329, 2020). "Logistic regression models were applied in order to determine the association of VDR polymorphisms with manifest HBV infection as well as with progression of related liver diseases mulin different genetic models." (PMID 31864292, 2019). "In order to study the influence of VDR variants on the clinical outcome of HBV-related liver diseases we compared laboratory parameters among HBV-infected patients with different genotypes of each of the VDR variants." (PMID 31864292, 2019). "The influences of VDR polymorphisms on the course as well as the pathogenesis of HBV-related liver diseases remain still controversial and need to be explored further." (PMID 31864292, 2019). "Among the four investigated VDR polymorphisms, ApaI is associated with clinical outcome and liver disease progression in Vietnamese HBV infected patients." (PMID 31864292, 2019). "This is the first report of an association between polymorphisms of the VDR gene and cytokine levels, severity of liver disease and survival in patients with liver cirrhosis." (PMID 30218108, 2018). "In several human studies, vitamin D receptor polymorphism is associated with hepatic disorders such as primary biliary cirrhosis and autoimmune hepatitis." (PMID 24130687, 2013). "Another study performed in India, showed that VDR a/a allele is associated with the severity of HBV-related liver disease and higher viral load." (PMID 27785252, 2013). "Elucidating the biological effect of VDR SNPs in CLD will contribute to more efficient management of CLD patients at different stages of liver disease, especially if certain SNPs are found to be associated with a pathogenic or beneficial effect on CLD in the context of personalized medicine." (PMID 37511164, 2023). "The clinical severity of liver disease is associated with VDR levels." (PMID 37511164, 2023). "VDR polymorphisms may influence immunomodulation by affecting cytokine levels, and may play a role in liver disease progression." (PMID 35955597, 2022). "Numerous nuclear receptors, including VDR, and their interplay have been linked to the development of liver disease, suggesting that vitamin D may influence disease by targeting VDR or other receptors." (PMID 35955597, 2022). "PBC is considered a Th1-mediated liver disease; therefore, reduced activity of 1,25(OH)2D3-dependent signaling pathways caused by the VDR polymorphisms might skew the immune response to the Th1 pathway, contributing to the development of PBC." (PMID 22690210, 2012). "Considering that vitamin D inhibits Th1-mediated responses, it has been hypothesized that impaired activity of VDR-mediated signaling pathways caused by VDR polymorphisms may direct the immune response to the Th1 pathway and may contribute to the development of liver disease." (PMID 35955597, 2022). "Moreover, polymorphisms of the vitamin D receptor gene and the interaction between downstream products and vitamin D concentration may be associated with the progression and severity of liver diseases." (PMID 31311491, 2019). "- Investigating the correlation between VDR polymorphisms and HBV-associated liver disease. - Utilizing SVM models to forecast various disease stages." (PMID 40061474, 2025). "In parallel, the vitamin D/VDR axis appears to be a critical modulator of the development and severity of a variety of liver diseases." (PMID 35955597, 2022).